LSM6 (LSM6 homolog, U6 small nuclear RNA and mRNA degradation associated)
Description:
Plays a role in pre-mRNA splicing as component of the U4/U6-U5 tri-snRNP complex that is involved in spliceosome assembly, and as component of the precatalytic spliceosome (spliceosome B complex). The heptameric LSM2-8 complex binds specifically to the 3'-terminal U-tract of U6 snRNA. Component of LSm protein complexes, which are involved in RNA processing and may function in a chaperone-like manner, facilitating the efficient association of RNA processing factors with their substrates. Component of the cytoplasmic LSM1-LSM7 complex, which is thought to be involved in mRNA degradation by activating the decapping step in the 5'-to-3' mRNA decay pathway (Probable).
Synonyms: YDR378C
Tractability: Small molecule: a structure with a bound ligand is known. PROTAC: ubiquitination databases record sites on it; its protein half-life has been measured.
Gene: Protein-coding gene on chromosome 4 (146,175,685 to 146,204,436, forward strand). Ensembl gene ENSG00000164167.
Subcellular location: Cytoplasm; Nucleus
Subcellular location (Human Protein Atlas): Actin filaments
Pathways (Reactome):
Metabolism of RNA: mRNA Splicing - Major Pathway; mRNA decay by 5' to 3' exoribonuclease
Gene Ontology:
Molecular function: protein binding; protein heterodimerization activity; RNA binding
Biological process: mRNA catabolic process; mRNA splicing, via spliceosome; deadenylation-dependent decapping of nuclear-transcribed mRNA; maturation of SSU-rRNA; RNA splicing; spliceosomal snRNP assembly; spliceosomal tri-snRNP complex assembly
Cellular component: cytoplasm; Lsm2-8 complex; nucleus; precatalytic spliceosome; spliceosomal complex; U2-type precatalytic spliceosome; U4/U6 x U5 tri-snRNP complex; cytosol; nucleolus; nucleoplasm; P-body; small nuclear ribonucleoprotein complex; sno(s)RNA-containing ribonucleoprotein complex; U4/U6 snRNP; U4atac/U6atac snRNP; U4atac/U6atac x U5 tri-snRNP complex; U6 snRNP; U6atac snRNP
Homologues: Orthologues: chimpanzee LSM6 (100% identical), dog LSM6 (100% identical), guinea pig LSM6 (100% identical), macaque LSM6 (100% identical), mouse Lsm6 (100% identical), rabbit LSM6 (100% identical), rat Lsm6 (100% identical), tropical clawed frog lsm6 (100% identical), zebrafish lsm6 (96% identical), pig LSM6 (88% identical), Drosophila melanogaster CG9344 (85% identical), Caenorhabditis elegans lsm-6 (79% identical). Paralogues in human: SNRPF (48% identical).
Diseases named in the same sentence as LSM6 in open-access papers:
LSM6 is named in the same sentence as 9 diseases in open-access papers, as found by Europe PMC text mining. Sharing a sentence is not in itself a finding about the gene and the disease. The quoted sentences say what the papers report.
breast carcinoma (3 papers, 2021 to 2024). "LSM6 participates in reducing E‐cadherin expression, thus promoting cell migration in breast cancer." (PMID 34586744, 2021).
breast tumors (1 paper, 2021). "Of interest, our findings through DNA methylation level analysis by using UALCAN database also support the consistent trend, which show LSM2, LSM4, LSM10 were upregulated in primary breast tumors, while LSM6 methylation levels were downregulated." (PMID 34638387, 2021). "Methylation levels of LSM2, LSM4, and LSM10 were upregulated in primary breast tumors, while LSM6 methylation levels were downregulated." (PMID 34638387, 2021).
Ewing sarcoma (1 paper, 2025). A small round cell tumor that lacks morphologic, immunohistochemical, and electron microscopic evidence of neuroectodermal differentiation. "While genes such as BCL11B and VRK1 are well characterized, others, such as IGF2BP1 and LSM6, remain poorly studied, yet they may offer valuable insights into the biology and vulnerabilities of Ewing sarcoma." (PMID 41444391, 2025).
nicotine dependence (1 paper, 2019). Physical and psychological dependence on nicotine. "Other genes highlighted in our EWAS with genetic variants associated with smoking-related phenotypes include LSM6 and CNTNAP2 associated with nicotine dependence and CACNA2D4 with pack years (indicator of lifelong accumulated smoking exposure)." (PMID 30611298, 2019).
LSM6 also shares sentences with these, for which no sentence is quoted: lung carcinoma (1 paper); ovarian carcinoma (1); prostate carcinoma (1); renal cell cancer (1); tumor (1).